PSME2 (proteasome activator subunit 2)
Description:
Implicated in immunoproteasome assembly and required for efficient antigen processing. The PA28 activator complex enhances the generation of class I binding peptides by altering the cleavage pattern of the proteasome.
Synonyms: PA28b; PA28beta; REGbeta
Tractability: PROTAC: ubiquitination databases record sites on it; its protein half-life has been measured.
Gene: Protein-coding gene on chromosome 14 (24,143,362 to 24,147,570, reverse strand). Ensembl gene ENSG00000100911.
Subcellular location (Human Protein Atlas): Nucleoplasm
Pathways (Reactome):
Immune System: Antigen processing: Ub, ATP-independent proteasomal degradation; Cross-presentation of soluble exogenous antigens (endosomes); ER-Phagosome pathway; Gene and protein expression by JAK-STAT signaling after Interleukin-12 stimulation
Metabolism of proteins: Proteasome assembly
Gene Ontology:
Molecular function: identical protein binding; protein binding; endopeptidase activator activity
Biological process: regulation of proteasomal protein catabolic process; cellular response to type I interferon; regulation of G1/S transition of mitotic cell cycle; response to oxidative stress
Cellular component: extracellular exosome; membrane; proteasome complex; cytoplasm; cytosol; nucleoplasm; proteasome storage granule; proteasome activator complex
Genetic constraint (gnomAD): Loss-of-function variants: 19 observed, 36.01 expected, observed/expected ratio (o/e) 0.53, 90% interval 0.37 to 0.77. The upper end of that interval is the gene's LOEUF score, 0.77, which puts it in group 3 of 6, group 1 being the genes least tolerant of losing a copy. Missense variants: 215 observed, 261.83 expected, observed/expected ratio (o/e) 0.82, 90% interval 0.73 to 0.92. Synonymous variants: 68 observed, 90.94 expected, observed/expected ratio (o/e) 0.75, 90% interval 0.61 to 0.92.
Homologues: Orthologues: dog PSME2 (97% identical), pig PSME2 (96% identical), guinea pig PSME2 (95% identical), rabbit PSME2 (95% identical), macaque PSME2 (95% identical), mouse Psme2 (94% identical), mouse Psme2b (94% identical), rat LOC100362709 (92% identical), zebrafish psme2 (64% identical), tropical clawed frog psme2 (58% identical), Drosophila melanogaster REG (33% identical), Caenorhabditis elegans psme-3 (32% identical). Paralogues in human: PSME1 (51% identical), PSME3 (36% identical).
Diseases named in the same sentence as PSME2 in open-access papers:
PSME2 is named in the same sentence as 45 diseases in open-access papers, as found by Europe PMC text mining. Sharing a sentence is not in itself a finding about the gene and the disease. The quoted sentences say what the papers report.
breast carcinoma (12 papers, 2009 to 2025). "Earlier reports have revealed three TAAs: CD74, IRF1, and PSME2, associated with immune cell infiltration in breast cancer." (PMID 38715072, 2024). "To further conform that deficiency of PSME2 repressed breast cancer proliferation, we used another breast cancer cell line, MCF-7." (PMID 38561760, 2024). "We used the IMMUcan database to analyze single-cell RNA data and examine the expression of PSMB8, BCL2, and PSME2 in the breast cancer immune microenvironment." (PMID 41403941, 2025). "We examined the clinical correlation of four key genes (PSMB8, BCL2, BMP5, and PSME2) with breast cancer prognosis." (PMID 41403941, 2025). "Among these nine screened genes, most of them were well-studied in breast cancer, except PSME2 and KCNJ11." (PMID 38561760, 2024). "PSME2, overexpressed in breast cancer, is involved in the proteasomal degradation of several proteins." (PMID 38715072, 2024). "Together, these data indicated that the knockdown of PSME2 repressed cell proliferation and clone formation in breast cancer cell lines." (PMID 38561760, 2024). "Then, both univariate and multivariate logistic regression analyses demonstrated that 6 genes regulated by the RUNX family had a significant relationship with the prognosis of breast cancer patients, including PSME2, ULBP2, IL18, TSLP, NPR3, and TRDV1." (PMID 36092942, 2022). "Functional similarity analysis further supports the central role of PSME2 in the biological processes of breast cancer, with its functional score approaching or exceeding the significance threshold, indicating that this gene plays an important role in regulating tumor-related signaling pathways." (PMID 41403941, 2025). "But the function of PSME2 in breast cancer cell lines was still unclear." (PMID 38561760, 2024). "Through in vitro experiment, we found PSME2 played an anti-tumor role in breast cancer." (PMID 38561760, 2024). "Therefore, changes in PSME2 expression not only reflect genomic structural variations but are also likely to impact immune recognition and tumor progression pathways, ultimately regulating the clinical outcomes of breast cancer." (PMID 41403941, 2025). "To assess whether CP and IP catalytic subunits were co-expressed in breast cancer samples, we performed a principal component analysis (PCA) on gene expression data for CP- and IP-encoding genes and regulatory subunits PA28α and PA28β (encoded by PSME1 and PSME2)." (PMID 27659694, 2016). "The TCGA-BRCA breast cancer dataset exhibits separate Kaplan–Meier survival curves (KM) for four notable genes (PSMB8, BCL2, BMP5, and PSME2)." (PMID 41403941, 2025). "Here, we knock-downed of PSME2 and KCNJ11 in two breast cancer cell lines, MDA-MB-231 and MCF-7 cells." (PMID 38561760, 2024). "PSME2, IL18 and NPR3 have been reported to have a close correlation with the proliferation, invasion, and migration of various tumors including breast cancer." (PMID 36092942, 2022). "STAT1 plays a key role in regulating the effect of chemotherapy; TYMP is considered to be a potential prognostic marker for ovarian cancer and breast cancer; GBP5, as an immune response regulator, can affect tumor progression; and PSME2 is closely related to the progression of various tumors." (PMID 40259929, 2025). "In the experiment part, the down-regulation of PSME2 inhibited cell growth ability and clone formation capability of breast cancer cells, while the down-regulation of KCNJ11 did not have any functions." (PMID 38561760, 2024). "PSME2, MAPK10, EIF4EBP1 were screened as the prognostic genes in breast cancer." (PMID 37035151, 2023).
clear cell renal cell carcinoma (6 papers, 2021 to 2025). "Increased PSME2 expression was linked to clear cell renal cell carcinoma invasion through regulatory autophagy." (PMID 39619148, 2024). "PSME2 overexpression has been linked to clear cell renal cell carcinoma invasion by blocking BNIP3-mediated autophagy." (PMID 35656090, 2022). "According to previous studies, PSME2 plays the role of promoting tumor progression in clear cell renal cell carcinoma, which is positively correlated with the ability of invasion regulating BNIP3-mediated autophagy." (PMID 36583022, 2022).
gastric cancer (4 papers, 2009 to 2023). A primary or metastatic malignant neoplasm involving the stomach. "Compared with paratumor tissues, the expression of PSME2 is upregulated in tumor tissues in multiple cancer types, such as gastric cancer, skin cutaneous melanoma, and urothelial cancer." (PMID 36583022, 2022). "In gastric cancer, knocked down PSME2 enhanced viability, clonogenicity, and tumorigenicity." (PMID 37529110, 2023).
melanoma (4 papers, 2022 to 2024). A malignant, usually aggressive tumor composed of atypical, neoplastic melanocytes. "Compared with those in the low-risk group, the melanoma patients in the high-risk group had high expression of S100A11 and CPC3 and low expression of PSME2, ARID5A, and SERPINE2 and had a shorter survival time." (PMID 35646893, 2022). "Clear PSME2 and TLR2 co-expression was evident in COAD, GBM, LIHC, PAAD, osteosarcoma, and melanoma." (PMID 38385075, 2024). "Spatial transcriptomic data from Spatial DB further confirmed that PSME2 expression patterns overlapped substantially with those of the macrophage marker CD68 and the M1 macrophage marker TLR2 in BRCA and melanoma, implied potential co-localization of these genes." (PMID 38385075, 2024). "In addition, PSME2 and other four gene markers for malignant cells (ARID5A, SERPINE2, GPC3, and S100A11) were combined to develop a prognostic signature in melanoma." (PMID 36583022, 2022).
diabetes (3 papers, 2016 to 2025). "It has been reported that increased plasma levels of APEX1, CD55, PSME2, and SERPINC1 are significantly associated with hypertension, and increased plasma levels of APEX1, CD55, GGCT, KRT17, PSME2, and SERPINC1 are associated with diabetes." (PMID 41156831, 2025).
gastric adenocarcinoma (3 papers, 2021 to 2024). "Knockdown of PSME2 is involved in the invasion and metastasis of gastric adenocarcinoma through upregulation of the chloride intracellular channel 1 (CLIC1)." (PMID 36226063, 2022). "When overexpressed, PSME2 is capable of suppressing the tumorigenic activity of both the TE-1 esophageal squamous cell carcinoma cell line as well as the MKN45 gastric adenocarcinoma (GA) cell line, consistent with its potential relevance as a therapeutic target in a range of cancers 5-7." (PMID 38385075, 2024).
lung carcinoma (3 papers, 2022 to 2025). "On the other hand, in breast and lung cancer cells, PSME2 downregulation reduced the viability, invasion, and migration." (PMID 37529110, 2023).
cervical cancer (2 papers, 2020 to 2025). A primary or metastatic malignant neoplasm involving the cervix. "The analysis showed that OAS2, KLHDC7B, STAT1, TYMP, PSME2 and GBP5 were significantly upregulated in cervical cancer cells compared with normal epithelial cells." (PMID 40259929, 2025).
endometrial cancer (2 papers, 2020 to 2021). Primary or metastatic malignant neoplasm involving the endometrium (mucous membrane that lines the endometrial cavity). "In contrast, PSME2 is up-regulated in endometrial cancer tissues compared to non-cancerous tissues and is closely related to the development of endometrial cancer." (PMID 34650966, 2021).
esophageal squamous cell carcinoma (2 papers, 2021 to 2022). Esophageal squamous cell carcinoma (ESCC) is a type of esophageal carcinoma (EC) that can affect any part of the esophagus, but is usually located in the upper or middle third. "PSME2 inhibits the growth, proliferation, and malignancy of esophageal squamous cell carcinoma cells and is considered a potential tumor suppressor." (PMID 36226063, 2022). "PSME2 has been reported to be significantly under-expressed in esophageal squamous cell carcinoma tissues, and up-regulated PSME2 expression significantly inhibited cell growth, proliferation, and malignancy of tumor cells." (PMID 34650966, 2021).
renal cell carcinoma (2 papers, 2022 to 2025). "Previous investigations have established that PSME2 overexpression facilitates renal cell carcinoma progression via BNIP3-mediated autophagic regulation." (PMID 41211066, 2025). "PSME2 has been less studied in cancer, and reports indicate that this gene is a typical poor prognostic marker in renal cell carcinoma and promotes malignant tumor progression by inhibiting autophagy." (PMID 36267313, 2022).
Sepsis (2 papers, 2016 to 2017). Sepsis is defined as life-threatening organ dysfunction caused by a dysregulated host response to infection. "MICB, PSMB2, PSMB8 and PSME2 showed consistently low level of expression in melioidosis cohort irrespective of other factors like comorbidities (risk factors), duration of clinical symptoms and antibiotic treatment, compared to other sepsis controls." (PMID 28628607, 2017). "MICB, PSMB2, PSMB8 and PSME2 were significantly up regulated in other sepsis cases compared to healthy controls while these target genes showed no significant differential expression in patients suffering from melioidosis compared to healthy controls." (PMID 28628607, 2017).
colitis (1 paper, 2025). Inflammation of the colon. "In parallel, western blotting of colon tissue lysates demonstrated that DSS colitis caused a significant increase in PSME2 protein, accompanied by a decrease in the tight junction protein claudin-1." (PMID 41211066, 2025). "PSME2 upregulation in UC and colitis mice correlated with disease severity." (PMID 41211066, 2025). "Our data demonstrated that PSME2 is consistently upregulated in UC patients, DSS-induced murine colitis, and LPS-challenged intestinal epithelial cells, suggesting a conserved role in intestinal inflammation." (PMID 41211066, 2025). "Multi-cohort transcriptomic analyses have consistently shown upregulation of PSME2 in UC patients, with similar trends observed in dextran sulfate sodium (DSS)-induced colitis models and clinical specimens." (PMID 41211066, 2025).
colon tumors (1 paper, 2024). "Impaired PSME2 expression has previously been tied to the ability of colon tumors to avoid immunosurveillance." (PMID 38385075, 2024).
cyst (1 paper, 2024). A sac-like closed membranous structure that may be empty or contain fluid or amorphous material. "Some factors (e.g., ICAM1, CCL20, PSME2, AXL) can also enhance proliferative signaling pathways (via MAPK/ERK, JNK, and JAK/STAT signaling, among others) that lead to cyst growth stimulation." (PMID 38385746, 2024).
influenza (1 paper, 2020). An acute viral infection of the respiratory tract, occurring in isolated cases, in epidemics, or in pandemics; it is caused by serologically different strains of viruses (influenzaviruses) designated A, B, and C, has a 3-day incubation period, and usually lasts for 3 to 10 days. "STAT1, TAP1, PSMB9, and PSME2, which are up-regulated preferentially by IFN-γ, were overexpressed only in influenza-specific cluster 1 (blue)." (PMID 32651212, 2020).
metastatic melanoma (1 paper, 2024). A melanoma that has spread from its primary site to another anatomic site. "When TIDE analyses were conducted based on levels of these CNVs, patients with metastatic melanoma, GBM, and BRCA exhibiting high PSME2 CNV levels exhibited higher survival rates, whereas the opposite was true in papillary KIRC." (PMID 38385075, 2024).
Myositis (1 paper, 2024). "Interestingly, XIRP2 and PSME2 were upregulated by tenfold and eightfold similarly to Ku + Myositis." (PMID 39012547, 2024).
osteosarcoma (1 paper, 2024). A usually aggressive malignant bone-forming mesenchymal neoplasm, predominantly affecting adolescents and young adults. "In osteosarcoma cells, overexpressing PSME2 significantly suppressed tumor proliferative, migratory, and invasive activity." (PMID 38385075, 2024). "Together, these results support the ability of PSME2 to significantly suppress osteosarcoma tumor proliferative, migratory, and invasive activity." (PMID 38385075, 2024). "The effects of PSME2 on the malignant phenotype of osteosarcoma were verified by in vivo and in vitro experiments." (PMID 38385075, 2024). "Screening efforts also successfully identified the PSME2-activating drug irinotecan, which can synergistically promote the death of osteosarcoma cells when combined with the chemotherapeutic drug paclitaxel." (PMID 38385075, 2024). "Osteosarcoma tissues exhibited higher PSME2 expression compared to adjacent normal tissues." (PMID 38385075, 2024). "As a biomarker of M1 macrophage infiltration, PSME2 expression levels may offer insight into tumor development and progression for a wide range of cancers including osteosarcoma, emphasizing its potential utility as a prognostic and therapeutic target worthy of further study." (PMID 38385075, 2024). "However, the effect of PSME2 on osteosarcoma progression is unknown." (PMID 38385075, 2024).
SARS-CoV infection (1 paper, 2012). "Interestingly, the temporal expression patterns of 4 IRGs (ISG15, IFI44, PSME2 and CCL2) were similar amongst the SARS-CoV infection-reinfection experiments (50 IRGs) and this list of 8 IRGs from the adjuvanted vaccine–challenge experiments." (PMID 23029269, 2012). "Moreover, four IRGs (ISG15, IFI44, PSME2 and CCL2) were expressed in common between the SARS-CoV infection-reinfection experiments and these 8 IRGs." (PMID 23029269, 2012).
triple-negative breast carcinoma (1 paper, 2024). An invasive breast carcinoma which is negative for expression of estrogen receptor (ER), progesterone receptor (PR), and human epidermal growth factor receptor 2 (HER2). "Relationships between PSME2 promoter methylation and CTLs were also assessed with TIDE in DLBC, STAD, OV, CESC, LUAD, and triple-negative breast cancer (TNBC)." (PMID 38385075, 2024).
tularemia (1 paper, 2015). Tularemia is an infection caused by the bacterium Francisella tularensis. "PSME2 is implicated in the immunoproteasome assembly and is upregulated in response to inflammatory conditions persistent in diseases such as tularemia, a bacterial disease related in pathology to TB34." (PMID 26469538, 2015).
ulcerative colitis (1 paper, 2025). An inflammatory bowel disease involving the mucosal surface of the large intestine and rectum. "The immunoproteasome regulatory component proteasome activator subunit beta (PSME2) plays a crucial role in immune regulation, yet its impact on intestinal barrier integrity in ulcerative colitis (UC) remains unclear." (PMID 41211066, 2025).
urothelial carcinoma (1 paper, 2022). A malignant neoplasm derived from the transitional epithelium of the urinary tract (urinary bladder, ureter, urethra, or renal pelvis). "Our previous studies found a co-expression network associated with CD8+ T lymphocyte invasion in urothelial carcinoma, which contains PSMB8, PSMB9, PSMB10, PSME2, IRF1 and other genes." (PMID 36700205, 2022).
virus infection (1 paper, 2023). "Of note, immunoproteasome subunit beta types PSMB8, PSMB9, and PSMB10, together with the PSME2 subunit of the immunoproteasome specific regulatory 11S cap structure, strongly indicated increased levels of immunoproteasomes with progressing virus infection." (PMID 37112941, 2023).